MSTN (myostatin)
Diseases named in the same sentence as MSTN in open-access papers (continued):
Sharing a sentence is not in itself a finding about the gene and the disease.
Insulin resistance (continued). "Similar results have been observed in type 2 diabetes (T2D) that the mRNA levels of MSTN were higher in the muscles of patients with T2D than in the control group and MSTN mRNA was correlated with homeostasis model assessment of insulin resistance (HOMA2-IR) and plasma IL-6 level." (PMID 37288303, 2023). "Myostatin appears to be one of the mediators of insulin resistance-induced skeletal muscle atrophy." (PMID 38255652, 2023). "Therefore, a balanced FGF21 level and a reduced myostatin level are also attracting attention as potential therapeutic targets for insulin resistance in T2D." (PMID 36981616, 2023). "Moreover, compared with wild-type HFD-fed mice, HFD-fed male MSTN-deficient mice had reduced plasma cholesterol and triglyceride levels and reduced plasma TNF-α levels by approximately 40 percent, and reduced insulin resistance." (PMID 37288303, 2023). "In addition to preventing muscle hypertrophy, MSTN has also been shown to induce insulin resistance in a mechanism dependent on nuclear factor kappa-light-chain-enhancer of activated B cells (NF-κB) and SMAD family member 3 (SMAD3)." (PMID 35330038, 2022). "Myostatin concentrations are elevated in sarcopenic obesity, negatively associated with insulin sensitivity indices and positively with measures of insulin resistance." (PMID 35287731, 2022). "It is worth noting that the mitochondrial dysfunction identified here may be related to increased myostatin, which can influence glucose metabolism and the development of insulin resistance." (PMID 35406665, 2022). "Evidence suggests that myostatin might mediate insulin resistance in a similar fashion that was observed during critical illness, namely decreased GLUT4 expression and translocation." (PMID 35922829, 2022). "Furthermore, we found that the secreted factors, myeloperoxidase was upregulated whereas apelin and myostatin were downregulated upon SARS-CoV-2 infection, which was potentially linked to the onset of insulin resistance." (PMID 34916489, 2021). "Furthermore, blocking myostatin was shown to increase muscle mass, ameliorate liver insulin resistance, and decrease hepatic steatosis in HFD mice." (PMID 34707570, 2021). "Conversely, the administration of recombinant myostatin induces insulin resistance." (PMID 34795636, 2021). "However, myostatin expression from GSE18732 was positively correlated with metrics of insulin resistance such as the Homeostasis Model Assessment (HOMA) 1/2." (PMID 32652899, 2020). "We had previously demonstrated that the insulin resistance-inducing effect of AgRP neuron activation occurs in part through an acute suppression of sympathetic nerve activation (SNA) of brown adipose tissue (BAT) to induce myostatin expression in BAT7." (PMID 31974377, 2020). "Since elevated plasma FFA is a major cause of insulin resistance in type 2 diabetes, we therefore used an in vitro FFA-induced insulin resistance cell culture model to further characterize the mechanisms by which APS attenuating myostatin expression." (PMID 24454989, 2013). "We therefore explored whether NF-κB participates in APS attenuating palmitate-induced myostatin expression and insulin resistance." (PMID 24454989, 2013). "The finding suggests the concept that myostatin may play a role in the development of insulin resistance." (PMID 24454989, 2013). "Recent animal studies suggest a role for myostatin in insulin resistance." (PMID 22615949, 2012). "We hypothesized that the relationship between myostatin and insulin sensitivity is independent of other risk factors for insulin resistance, such as BMI and visceral adipose tissue (VAT)." (PMID 39261976, 2024). "Thus, it remains unclear whether changes in the expression and abundance of myostatin are driven by excess adiposity per se or are influenced by age-related changes such as development of insulin resistance and declining skeletal muscle mass and function." (PMID 37801203, 2024).
Insulin resistance (continued). "Hence, it is not clear whether the associated metabolic phenotype, i.e. strong protection against diet-induced insulin resistance, hepatosteatosis, and atherosclerosis, is directly related to myostatin signaling or secondary to the extreme muscle hypertrophy." (PMID 23936482, 2013). "Alternatively, insulin resistance may result in derepression of myostatin via constitutive activation of FoxO1; this model would be consistent with the observation of elevated myostatin in insulin resistant type 2 diabetic patients and non-obese hyperinsulinemic subjects." (PMID 24381559, 2013). "Interestingly, recent observations in animal models suggest that myostatin is involved in the regulation of energy metabolism as hypermuscular myostatin knock-out mice have reduced fat mass and are protected from dietary-induced insulin resistance." (PMID 22615949, 2012). "First, increased myostatin expression and more impressively secretion has been observed in muscle and adipose tissue samples derived from obese and extremely obese women, and increased circulating levels of myostatin in this cohort were found to be correlated with insulin resistance." (PMID 20593012, 2010). "In the esophagus, coordinated changes in methylation and expression implicate MSTN in metabolic adaptation and immune regulation, potentially via AMPK/NOX4/PI3K/AKT signaling, which has established links to glucose homeostasis and insulin resistance." (PMID 40699830, 2025). "While some (such as FGF-21, irisin, adiponectin, klotho, and osteocalcin) have protective effects, others (such as myostatin, fetuin-A, visfatin, and ANGPTL3) exacerbate insulin resistance, inflammation, and fibrosis." (PMID 41373697, 2025). "Genes such as MSTN, IFNA13, ATP8B3, and GABBR2 showed methylation changes, potentially influencing insulin resistance, adiposity, and innate immune response in offspring." (PMID 40507105, 2025). "Given that skeletal muscle mRNA expression of myostatin was increased and insulin sensitivity was impaired in participants with excess adiposity in our in vivo study, we next sought to examine whether the induction of insulin resistance can directly affect myostatin expression." (PMID 37801203, 2024). "However, an association between serum myostatin levels and insulin sensitivity independent of body composition and other risk factors for insulin resistance, namely higher BMI, higher VAT, and male sex, has not been reported using a validated myostatin LC–MS/MS assay." (PMID 39261976, 2024). "MSTN levels were positively correlated with FBG levels and the homeostatic model assessment of insulin resistance (HOMA-IR) index." (PMID 39124846, 2024). "Interestingly, inhibiting the level of MSTN could relieve insulin resistance and diabetes." (PMID 37288303, 2023). "We hypothesized that myostatin mRNA expression and systemic protein levels are elevated during the early and acute phase of critical illness in patients with ICUAW and that this is associated with muscle atrophy, development of CIP and CIM and insulin resistance." (PMID 35922829, 2022). "Therefore, myostatin could be a potent target for the treatment of diabetes and insulin resistance." (PMID 24454989, 2013). "Finding GDF8 (myostatin) to be upregulated in healthy first degree relatives in this study suggests that this factor could play an initiating role in the muscle wasting observed in many diabetic patients and potentially in the development of insulin resistance in the prediabetic stage." (PMID 19668377, 2009). "However, in the setting of insulin resistance, the PI3K/AKT/FoxO1 pathway becomes inactive, leading to elevated FoxO1 activity, increased MSTN expression, and the subsequent development of skeletal complications associated with T2DM." (PMID 40136413, 2025). "In addition, myostatin impairs insulin signaling by downregulating IRS-1 and GLUT4 expression, aggravating insulin resistance and glucose intolerance." (PMID 41305665, 2025).
Insulin resistance (continued). "The changes in myostatin levels after the intervention were positively correlated with the changes in insulin levels and also positively correlated with the changes in the HOMA-IR index, a marker of insulin resistance." (PMID 40806137, 2025). "Skeletal muscle myostatin mRNA expression is uniquely upregulated in aged adults with excess adiposity and insulin resistance but not by ageing alone." (PMID 37801203, 2024). "Irisin and myostatin concentrations were also lower in acromegalics with insulin resistance than without (2.80 vs. 4.18 μg/ml, p = 0.047; 81.46 vs. 429.58 ng/L, p = 0.018, respectively)." (PMID 34795636, 2021). "Although insulin resistance has been induced by injecting myostatin into mice, this does not prove that the normal basal level of myostatin is a significant determinant of insulin sensitivity." (PMID 21390326, 2011). "However, after controlling for BMI, VAT, and sex, myostatin/ALM was negatively associated with insulin sensitivity by Matsuda index (p = 0.03), although the association with insulin resistance by HOMA‐IR remained not significant (p = 0.07)." (PMID 39261976, 2024). "Myostatin was also found to signal via the nuclear factor kappa-light-chain-enhancer of activated B cells (NF-κB), which, together with SMAD3 activation, could affect glucose uptake inducing insulin resistance." (PMID 32796600, 2020). "Injection of APS into the SMs of non-insulin-dependent type 2 diabetic KKAy mice ameliorated insulin resistance and hyperglycemia, and reduced MSTN levels in SM, which demonstrated APS might improve insulin sensitivity and reduce SM MSTN levels by downregulating the ROS-ERK-NF-κB pathway." (PMID 35812316, 2022). "Interestingly, neither serum nor muscle myostatin expression was related to HbA1c lending support for a potential role of myostatin in the development of insulin resistance, as previously suggested, that is distinct from its effects on systemic glycemic control as measured by HbA1c." (PMID 32652899, 2020). "We assessed whether plasma concentrations of three known myokines [myonectin, myostatin, and fibroblast-derived growth factor 21 (FGF-21)] would be associated with direct and indirect indicators of insulin resistance (IR) in individuals who did not have a diagnosis of diabetes." (PMID 29445355, 2018).
muscular dystrophy (80 papers, 2007 to 2025). Muscular dystrophy (MD) refers to a group of more than 30 genetic diseases characterized by progressive weakness and degeneration of the skeletal muscles that control movement. "Inhibiting myostatin signaling using adeno-associated viral expression of a secreted myostatin dominant-negative peptide increased muscle mass and reduced muscle fibrosis in a Golden Retriever model of muscular dystrophy (GRMD) after 13 months of exposure." (PMID 34516828, 2021). "Mdx mice deficient in myostatin have an improved muscular dystrophy phenotype and increased mass compared to mdx mice." (PMID 27148972, 2016). "To investigate this issue, we examined the effect of blocking myostatin signaling in dysferlin-deficient (Dysf−/−) mice, which is a model for limb-girdle type 2B and Miyoshi muscular dystrophies." (PMID 26206886, 2015). "The results from these studies have been mixed, with most benefits of myostatin inhibition being observed in the dystrophin-deficient mdx mouse, a model of inherited human muscular dystrophy." (PMID 24504412, 2014). "Myostatin blockage at an early stage in a model of δ-sarcoglycan-deficient muscular dystrophy was effective in reducing muscle loss and fibrosis, and in improving regeneration." (PMID 19538713, 2009). "Therefore, muscular dystrophy except for dystrophin deficiency induces the enhancement of myostatin-dependent signaling." (PMID 25221510, 2014). "Myostatin also regulates muscle mass in adult mice: Inhibition of myostatin by injection of neutralizing antibodies or antagonists causes an increase in skeletal muscle mass in both healthy adult mice and in mouse models of muscular dystrophy." (PMID 19295913, 2009). "Therefore, myostatin downregulation may serve as a potentially important mechanism for treating diseases associated with muscle wasting, such as muscular dystrophy." (PMID 23717655, 2013). "However, there is the possibility that myostatin inhibition in the heart could interfere with cardiac adaptation to underlying cardiac disease that may occur with aging and a subset of the muscular dystrophies." (PMID 20161803, 2010). "Before the Acceleron study, other myostatin inhibitors had been studied for their effect on muscular dystrophies." (PMID 40717734, 2025). "Clinical trials utilizing MSTN inhibitors began in the early 2000s, primarily aiming to increase muscular function and survivability in muscular dystrophies." (PMID 39340593, 2025). "Myostatin is a negative regulator of muscle growth, and aptamers that bind to myostatin-expressing cells can target miRNA therapies to enhance muscle regeneration or treat muscular dystrophy." (PMID 39684593, 2024). "Myostatin inhibition has also demonstrated therapeutic potential in more complex mouse models involving muscle wasting with disorders including muscular dystrophy, cachexia and chemotherapy, and aging." (PMID 36646717, 2023). "MSTN has garnered significant interest in medical and biological breeding applications, particularly in the treatment of muscular dystrophy and livestock breeding." (PMID 37512543, 2023). "The inhibition of myostatin is currently sought for the treatment of skeletal muscle-related disorders such as muscular dystrophy, sarcopenia and cancer cachexia." (PMID 37570625, 2023). "Myostatin, an important negative regulator of muscle mass, is a therapeutic target for muscle atrophic disorders such as muscular dystrophy." (PMID 37570625, 2023). "Here, we report that the EtOAc derived fractions of G. uralensis reduced the expressions of MSTN, Atrogin1, and MurF1, which suggests it has therapeutic potential against muscle wasting in muscular dystrophy." (PMID 33467209, 2021). "This can be an alternative approach to strengthen myogenesis in addition to previously reported therapeutic strategies against muscular dystrophies, such as stem cell transplantation, the inhibition of myostatin, and IGF-1 supplementation." (PMID 34490258, 2021).
muscular dystrophy (continued). "Unsurprisingly, in muscular dystrophy diseases, including sarcopenia, muscular dystrophy, and cancer-related cachexia, controlling myostatin signaling has become an attractive prospect for increasing functional muscle mass." (PMID 34590222, 2021). "Crossing myostatin-null with other models of muscular dystrophy has occasionally been the preceding study to pharmacological interventions." (PMID 33802348, 2021). "In the past 20 years, myostatin, a negative regulator of muscle mass, has attracted attention as a potential therapeutic target in muscular dystrophies and other conditions." (PMID 33802348, 2021). "For the last 20 years, one of the most promising therapeutic subjects in the field of muscular dystrophies has been myostatin." (PMID 33802348, 2021). "Myostatin is a known regulator of fibroblast activation and apoptosis, with anti-myostatin agents shown to have an anti-fibrotic effect in other models of muscular dystrophy." (PMID 32194441, 2020). "Myostatin is a negative regulator of muscle mass, and inhibition of myostatin has been demonstrated to improve symptoms in models of muscular dystrophy." (PMID 32194441, 2020). "Concerning follistatin, the pivotal function of this protein is the inhibition of the myostatin pathway in order to regulate the muscle mass in muscular dystrophies." (PMID 32961888, 2020). "Several biopharmaceutical agents capable of antagonizing binding of myostatin or myostatin and activin A have entered clinical development for muscle-wasting diseases or muscular dystrophies." (PMID 30368252, 2018). "Active levels of myostatin were reduced in transgenic mdx muscle, providing a mechanism by which this protein exerts its protective effects in muscular dystrophy." (PMID 27148972, 2016). "This study shows that LTBP4 modifies muscular dystrophy based on its ability to scaffold and regulate multiple TGFβ family members including myostatin." (PMID 27148972, 2016). "Based partly on these results, myostatin inhibitors are in development for use in human muscular dystrophies." (PMID 27047655, 2016). "Remarkably, preclinical studies have shown that pharmacological downregulation of myostatin signaling attenuates the pathological phenotype in sarcopenic rodents and several mouse models of muscular dystrophy." (PMID 26321948, 2015). "One indication for which myostatin inhibition is being tested as a potential therapy is muscular dystrophy." (PMID 26206886, 2015). "Upregulation of myostatin signaling is also commonly observed in both muscular dystrophy and sarcopenia." (PMID 26321948, 2015). "The trial study concluded that the systemic administration of myostatin inhibitors was relatively safe and that more potent inhibitors for stimulating muscle growth in muscular dystrophy should be considered." (PMID 25221510, 2014). "There have been several studies dealing with the adaptive changes in myostatin expression of muscular dystrophy." (PMID 25221510, 2014). "As the aim of this study is to examine the effectiveness of ATCOL-mediated administration of myostatin-targeting siRNA into skeletal muscles as a future treatment remedy of muscular dystrophy, we chose the mCAV-3Tg mouse as a muscle dystrophy model." (PMID 23717655, 2013). "In this study, we evaluate the effectiveness of atelocollagen (ATCOL)-mediated application of siRNA targeting myostatin (Mst), a negative regulator of skeletal muscle growth, into skeletal muscles of muscular dystrophy model mice." (PMID 23717655, 2013). "This information is especially important in light of the ongoing clinical trials using myostatin inhibition via an antibody approach as a potential treatment for several types of muscular dystrophy." (PMID 20419100, 2010). "The mdx mouse model of Duchenne muscular dystrophy was utilized to examine the effect of myostatin inhibition on the progression of muscular dystrophy." (PMID 20161803, 2010).